WNT5B (Wnt family member 5B)
Description:
Ligand for members of the frizzled family of seven transmembrane receptors. Probable developmental protein. May be a signaling molecule which affects the development of discrete regions of tissues. Is likely to signal over only few cell diameters (By similarity).
Tractability: Antibody: its Gene Ontology location is reachable by antibodies, with high confidence; UniProt places it where antibodies can reach, with medium confidence; UniProt predicts a signal peptide or a membrane-spanning region. PROTAC: ubiquitination databases record sites on it.
Gene: Protein-coding gene on chromosome 12 (1,529,854 to 1,647,243, forward strand). Ensembl gene ENSG00000111186.
Subcellular location: Secreted, extracellular space, extracellular matrix
Subcellular location (Human Protein Atlas): Vesicles; Predicted to be secreted
Pathways (Reactome):
Signal Transduction: PCP/CE pathway; WNT ligand biogenesis and trafficking
Gene Ontology:
Molecular function: signaling receptor binding; cytokine activity; frizzled binding
Biological process: chondrocyte differentiation; positive regulation of cell migration; canonical Wnt signaling pathway; cell fate commitment; cellular response to retinoic acid; fat cell differentiation; lens fiber cell development; muscle cell differentiation; neuron differentiation; positive regulation of convergent extension involved in gastrulation; positive regulation of non-canonical Wnt signaling pathway; Wnt signaling pathway
Cellular component: extracellular exosome; extracellular matrix; endocytic vesicle membrane; endoplasmic reticulum lumen; extracellular region; Golgi lumen; plasma membrane; cell surface
Genetic constraint (gnomAD): Loss-of-function variants: 18 observed, 36.1 expected, observed/expected ratio (o/e) 0.5, 90% interval 0.34 to 0.74. The upper end of that interval is the gene's LOEUF score, 0.74, which puts it in group 3 of 6, group 1 being the genes least tolerant of losing a copy. Missense variants: 424 observed, 517.72 expected, observed/expected ratio (o/e) 0.82, 90% interval 0.76 to 0.89. Synonymous variants: 213 observed, 215.19 expected, observed/expected ratio (o/e) 0.99, 90% interval 0.88 to 1.11.
Homologues: Orthologues: chimpanzee WNT5B (99% identical), macaque WNT5B (98% identical), rabbit WNT5B (95% identical), mouse Wnt5b (94% identical), rat Wnt5b (94% identical), guinea pig WNT5B (94% identical), pig WNT5B (92% identical), dog WNT5B (92% identical), tropical clawed frog wnt5b (85% identical), zebrafish wnt5b (80% identical), Drosophila melanogaster Wnt5 (47% identical), Caenorhabditis elegans cwn-2 (44% identical), and 4 more. Paralogues in human: WNT5A (81% identical), WNT2B (50% identical), WNT2 (46% identical), WNT3A (45% identical), WNT3 (45% identical), WNT4 (44% identical), WNT7A (43% identical), WNT7B (43% identical), WNT10A (41% identical), WNT16 (40% identical), WNT6 (40% identical), WNT1 (38% identical), and 6 more.
Diseases named in the same sentence as WNT5B in open-access papers:
WNT5B is named in the same sentence as 82 diseases in open-access papers, as found by Europe PMC text mining. Sharing a sentence is not in itself a finding about the gene and the disease. The quoted sentences say what the papers report.
breast carcinoma (23 papers, 2012 to 2025). "WNT5B is implicated in various human cancers, such as breast cancer, colorectal cancer and lung cancer." (PMID 38689429, 2024). "WNT5B overexpression was previously detected in several tumor types (such as non-small cell lung cancer, chronic lymphocytic leukemia, and basal-like breast cancer) and was associated with cancer aggressiveness and a poorer prognosis." (PMID 34572445, 2021). "Most importantly, this delicate regulation by WNT5B didn’t limited in a particular cell model; it was fundamentally associated with patients’ metastasis and disease-free survival in a larger population with breast cancer." (PMID 24564888, 2014). "In contrast to WNT5B, many publications show WNT5A as a tumor suppressor in breast cancer, correlating its loss with a worse prognosis." (PMID 34017835, 2021). "WNT5B is overexpressed in the majority of Triple Negative (TNBC)/Basal-Like Breast Cancer (BLBC) cell lines and primary patient samples and is correlated with a worse prognosis." (PMID 34017835, 2021). "While a variety of studies have identified roles for other Wnt signaling factors in basal-like breast cancer, few exist for WNT5B and TEAD4." (PMID 30484104, 2019). "To explore the correlation between WNT5B and basal-like phenotype, we selected 34 breast cancer cell lines with known molecular typing based on CCLE." (PMID 31462314, 2019). "Wnt5a and Wnt5b have been proven as regulators of EMT in breast cancer, and we also corroborated this conclusion." (PMID 31462314, 2019). "Collectively, both the in vitro and in vivo results suggested that WNT5B-initiated MCL1 signaling dominantly controlled the overall outcome of breast cancer patients, especially in TNBC." (PMID 24564888, 2014). "WNT5B mRNA was identified as one of the overexpressed gene in TNBC among 779 breast cancer tissues in TCGA data analysis." (PMID 24564888, 2014). "We validated the microarray results by immunohistochemistry (IHC) staining of WNT5B in breast cancer tissue array samples." (PMID 24564888, 2014). "A decrease in Wnt5a and Wnt5b suppressed invasion in breast cancer." (PMID 40569965, 2025). "In breast cancer cells, depletion of WNT5B by RNAi decreased the formation of mammospheres, which could be rescued by overexpression of TAZ, indicating an interplay between Wnt and Hippo signaling on breast cancer initiation." (PMID 36982422, 2023). "In addition, WNT5B was found to be amplified in 3.2% of breast cancers, although the type of breast cancer with WNT5B amplification was not described." (PMID 34017835, 2021). "However, it was shown that WNT5B is suppressed by miR145-5p in three basal-like breast cancer cell lines." (PMID 34017835, 2021). "Furthermore, transgenic mice overexpressing β-hCG have been shown to develop multiple neoplasms, including breast cancer, also showing that hCG can up-regulate Wnt7b and Wnt5b, thus contributing to pregnancy-induced breast cancer in humans." (PMID 33572731, 2021). "Similarly, WNT5B has been very recently identified as a key regulator governing the aggressive basal-like phenotype in breast cancers." (PMID 33291363, 2020). "Wnt ligands, such as WNT3A, WNT9A, WNT11 and WNT5B were highly amplified in breast cancers." (PMID 31462314, 2019). "Furthermore, expression of WNT pathway genes correlated with estrogen receptor (ER) expression, especially WNT5a and WNT5b, with approximately 50% of breast cancer tissues overexpressing these genes." (PMID 27487128, 2016). "We further screened the WNT5B expression in breast cancer cell lines." (PMID 24564888, 2014). "Therefore, the roles of WNT5A and WNT5B in breast cancer need further research." (PMID 34017835, 2021). "PTK7 expression in breast cancer was significantly positively correlated with COL1A1, FN1, WNT5B, MMP11, MMP14 and SDC1 in breast cancer." (PMID 34367983, 2021).
breast carcinoma (continued). "b mRNA expression of WNT3A, WNT3, WNT5A, WNT5B, and WNT11 in five different breast cancer subtypes based on bc-GenExMiner v4.1 according to the Sørlie’s subtypes (****p < 0.0001; Red star: the former > the latter; Green Star: the former < the latter)." (PMID 31462314, 2019). "WNT5B has been shown to interact with ROR2 in osteosarcoma, while preliminary results indicate that WNT11 could be a ligand of ROR2 in breast cancer." (PMID 35246138, 2022). "Co-expression analysis and gain- or loss-of-function of PTK7 in TNBC cell lines revealed that PTK7 participates in EGFR/Akt signaling regulation and associated with extracellular matrix organization and migration genes in breast cancer, including COL1A1, FN1, WNT5B, MMP11, MMP14 and SDC1." (PMID 34367983, 2021). "In summary, Wnt5b governs the phenotype of BLBC by activating both canonical and non-canonical Wnt signaling, and should be a promising theranostic target of basal-like breast cancer." (PMID 31462314, 2019). "To confirm differential gene expression levels in the three breast cancer subtypes, Her2+, ER + and TNBC, we selected 6 genes (ITGA3, ITGA5, OXTR, WNT5B, BCAR1, FZD1) with significantly different levels of expression based on our microarray studies and validated their expression levels by qRT-PCR." (PMID 22954256, 2012). "Most importantly, 5 genes were found to be associated with all of the most highly enriched GO terms and KEGG pathways: WNT5A, WNT6, WNT11, WNT5B and LAMA1, which suggested that WNTs may be essential targets of ATBF1 and may contribute to breast cancer tumorigenesis." (PMID 36476423, 2022). "The regulation of WNT5B expression in breast cancer (or other cell types) is not well-studied." (PMID 34017835, 2021).
melanoma (9 papers, 2012 to 2025). A malignant, usually aggressive tumor composed of atypical, neoplastic melanocytes. "To look for further evidence for the importance of Notch3 and WNT5B in the aggressiveness of melanoma, we performed Kaplan-Meier survival association analyses for both genes using the 442 patient cohort from TCGA." (PMID 37971882, 2024). "A bi-directional DLL4/Notch3/WNT5B-dependent signaling cascade underlies crosstalk between melanoma and lymphatic endothelial cells and promotes melanoma lymphatic metastasis." (PMID 37971882, 2024). "The molecular and functional changes in LECs induced by melanoma cells are mediated by the Delta-like protein 4 (DLL4)/Notch3/WNT5B signaling axis." (PMID 41511312, 2025). "We next confirmed that WNT5B mRNA was upregulated upon LEC coculture in the metastatic melanoma cell lines WM852 and WM165." (PMID 37971882, 2024). "The melanoma-derived WNT5B then contributes to the functional changes in LECs in a paracrine manner." (PMID 37971882, 2024). "The dispersion is expected to result in more opportunities for melanoma cells to communicate with the mouse lymphatic vasculature in a WNT5B-dependent manner and thereby to promote lymphatic dissemination." (PMID 37971882, 2024). "This supported the role of WNT5B in promoting the metastatic potential of melanoma cells through its effects on LECs." (PMID 37971882, 2024). "Together, these data demonstrate that Notch3 acts as an upstream positive regulator of WNT5B in the metastatic melanoma cell lines WM852 and WM165." (PMID 37971882, 2024). "Our data also demonstrated that metastatic samples from a patient cohort with particularly aggressive melanoma showed a significantly higher correlation for Notch3 and WNT5B coexpression when compared with the primary tumors." (PMID 37971882, 2024). "To that end, we first treated WM852 melanoma cells with control siRNA or siRNA targeting WNT5B prior to the 48-hour coculture with LECs and subsequent cell separation." (PMID 37971882, 2024). "This was further supported by mRNA analysis of a 442-patient melanoma data set obtained from TCGA, altogether supporting the importance of the Notch3/WNT5B axis in melanoma aggressiveness." (PMID 37971882, 2024). "Specifically, we show that DLL4, expressed on the LEC surface, activates Notch3 in melanoma cells, which in turn triggers WNT5B transcription and protein expression in melanoma cells." (PMID 37971882, 2024). "Notch3 binds to the WNT5B gene promoter region, thus confirming its role as a transcriptional activator of WNT5B in melanoma cells." (PMID 37971882, 2024). "As expected, we observed strong induction of some Wnts, whereas others, such as Wnt5a and Wnt5b, which were upregulated in several melanoma cell lines, were surprisingly downregulated in the analyzed melanoma cell lines compared to those in NHEMs." (PMID 38388496, 2024). "Together, these functional assays demonstrate that WNT5B expressed and secreted by the melanoma cells contributes to the functional changes in LECs*." (PMID 37971882, 2024). "This study elucidated WNT5B as a key molecular factor mediating bidirectional crosstalk between melanoma cells and lymphatic endothelium and promoting melanoma metastasis." (PMID 37971882, 2024). "We identified WNT5B as a key component of the bidirectional, reciprocal melanoma cell–LEC crosstalk." (PMID 37971882, 2024). "WNT5B upregulation was mediated by Notch3 activation induced in melanoma cells by direct interaction with LECs upon coculture." (PMID 37971882, 2024). "Coculture with the melanoma cells depleted of WNT5B significantly reduced the sprouting of LEC spheroids." (PMID 37971882, 2024). "WNT5B did not significantly correlate with patient survival, potentially due to Notch3 being the upstream regulator of WNT5B transcription and production in the melanoma cells." (PMID 37971882, 2024).
melanoma (continued). "The mouse ear pinna xenograft assay indicated that WNT5B facilitates the LEC-primed melanoma cell escape from the primary injection site and translocation to the proximate draining lymph nodes." (PMID 37971882, 2024). "This further supports our findings from the functional assays that the Notch3/WNT5B axis has an important role in melanoma aggressiveness." (PMID 37971882, 2024). "WNT5B, a paracrine signaling molecule upregulated in melanoma cells upon LEC interaction, was found to contribute to the functional changes in LECs." (PMID 37971882, 2024). "Here, we report that the DLL4/Notch3/WNT5B signaling axis induced upon melanoma cell and LEC interaction promotes melanoma metastasis via its effects on LEC phenotype and function." (PMID 37971882, 2024). "In this data set, WNT5B, a gene encoding a secreted signaling molecule, was found to be highly upregulated in the LEC-cocultured WM852 melanoma cells." (PMID 37971882, 2024). "In addition, DLL4 was recently identified as a an upstream inducer of the Notch3/WNT5B axis mediating bidirectional prometastatic crosstalk between melanoma and lymphatic endothelial cells." (PMID 39951484, 2025). "Furthermore, expression of Notch3 and WNT5B shows a significant, positive correlation at the mRNA level in a 442-patient melanoma data set obtained from The Cancer Genome Atlas (TCGA)." (PMID 37971882, 2024). "To further characterize the role of WNT5B in melanoma progression, we chose to use an in vivo tumor model where melanoma cells are injected intradermally into the mouse ear pinna, which is rich in lymphatic capillary networks and feasible to image by confocal microscopy." (PMID 37971882, 2024). "Depletion of WNT5B in the melanoma cells could partially restore the tube formation ability of LECs* and the barrier function of the LEC* layer." (PMID 37971882, 2024). "Finally, DLL4, a Notch ligand expressed in LECs, was identified as an upstream inducer of the Notch3/WNT5B axis in melanoma." (PMID 37971882, 2024). "We next investigated whether Notch3 and WNT5B expression would correlate in melanoma patient samples." (PMID 37971882, 2024). "It is therefore possible that WNT5B is one of the key players contributing to the first metastatic steps in melanoma progression, and our results imply that melanoma cells require a direct interaction with LECs in the tumors for the initiation of the metastatic cascade." (PMID 37971882, 2024). "Notch ligand DLL4 is a potent inducer of Notch3 and WNT5B in melanoma." (PMID 37971882, 2024). "Melanoma cell–derived WNT5B contributes to the functional changes in LECs." (PMID 37971882, 2024). "Moreover, WNT5B transcription was regulated by Notch3 in melanoma cells following the coculture with LECs, and Notch3 and WNT5B were coexpressed in melanoma patient primary tumor and metastasis samples." (PMID 37971882, 2024). "WNT5B facilitates melanoma cell escape from the primary injection site." (PMID 37971882, 2024). "Moreover, our results demonstrate that the melanoma-derived WNT5B participates in inducing the functional changes in LECs in a paracrine manner." (PMID 37971882, 2024). "In melanoma cell lines, knockdown of WNT5B and WNT11 reduced the formation of melanospheres." (PMID 36982422, 2023). "Additionally, a reduction in the invasiveness of melanoma cells in a collagen invasion assay upon knockdown of WNT5B and WNT11 was observed." (PMID 36982422, 2023). "Therefore, we tested whether Notch3 would function as the upstream regulator of WNT5B expression in the cocultured melanoma cells." (PMID 37971882, 2024). "WNT5B, a key molecular factor in TME, involves bidirectional crosstalk between melanoma cells and LECs and promotes melanoma metastasis." (PMID 41511312, 2025). "Also, WNT5B may decrease VE-cadherin expression, having a pro-metastatic role and causing functional and transcriptional changes in lymphatic endothelial cells in oral squamous cell carcinoma (OSCC) and melanoma." (PMID 39202425, 2024).
melanoma (continued). "We found that melanoma cells induced metastasis-promoting molecular and functional changes in LECs mediated by the DLL4/Notch3/WNT5B signaling axis." (PMID 37971882, 2024). "Further, the genes upregulated upon Rec KD in A375 cells included factors such as WNT5B and GSK3B, which are known to induce the EMT-like process and are activated when melanoma gets relapsed to metastasis after failed treatment." (PMID 33202765, 2020). "NOTCH3 depletion in the monotypic melanoma cells, however, did not significantly affect the basal level of WNT5B." (PMID 37971882, 2024). "Moreover, melanoma cells derived from LEC coculture escaped efficiently from the primary site to the proximal tumor-draining lymph nodes, which was impaired upon WNT5B depletion." (PMID 37971882, 2024). "We also analyzed WNT5B induction following LEC coculture with a nonmetastatic melanoma cell line, WM793, but did not see any increase in WNT5B mRNA." (PMID 37971882, 2024). "Fifty-five primary tumor samples and 44 metastasis samples from these 55 melanoma patients were stained with antibodies against WNT5B and Notch3." (PMID 37971882, 2024). "When compared with vehicle-treated cocultures, the DAPT treatment significantly reduced the upregulation of WNT5B mRNA levels in WM852 and WM165 cells cocultured with LECs, further supporting a key role for Notch3 in regulating WNT5B expression in the metastatic WM852 and WM165 melanoma cells." (PMID 37971882, 2024). "To provide further evidence of a true lymph node metastasis of the siCtrl* cells and its dependence on WNT5B, we analyzed the presence of GFP-expressing siCtrl, siCtrl*, and siWNT5B* WM852 cells in the superficial cervical and inguinal lymph nodes by FACS 8 and 14 days after melanoma cell injection." (PMID 37971882, 2024).